EPHA2 (EPH receptor A2)
Diseases named in the same sentence as EPHA2 in open-access papers (continued):
Sharing a sentence is not in itself a finding about the gene and the disease.
melanoma (continued). "On the other hand, EPHA2 overexpression in melanoma tissues was correlated with increased melanoma thickness and increased tumor cell proliferative capacity, assessed as the Ki67 index." (PMID 34445116, 2021). "Curcumin was shown to inhibit tumor growth and angiogenesis in melanoma cells by downregulating EPHA2." (PMID 34299042, 2021). "In this study, we demonstrated that CH is efficient in blocking the amoeboid motility of metastatic melanoma cells by decreasing EphA2 expression and RhoA activation." (PMID 34298765, 2021). "The resistance to BRAF inhibitors, which is crucial for melanoma prognosis, is caus-ally associated with a mesenchymal-to-amoeboid transition (MAT) and shown as elicited by ligand-independent EphA2 activation." (PMID 33572284, 2021). "EPHA2, which is highly expressed in dedifferentiated/invasive melanoma cells, stimulates RhoA activity and promotes amoeboid migration." (PMID 33802847, 2021). "Knockdown of not only EphA2 but also VE-cadherin abrogated VM formation in aggressive melanoma cells." (PMID 31936664, 2020). "Instantaneous knockout of EphA2 in aggressive melanoma cells abrogates tubular structure formation in these tumor cells." (PMID 32116702, 2020). "We found that expression of EphA2 was much lower in vemurafenib-resistant melanoma cells compared to parent cells." (PMID 31581483, 2019). "Melanoma tumor samples from patients taken prior to or after treatment with BRAFi and MEKi showed very high expression of EphA2 in both BRAFV600E and BRAFWT melanomas." (PMID 31581483, 2019). "Metastatic melanoma-specific delivery of MEK inhibitors can be achieved by targeting overexpressed EphA2 receptors in vemurafenib-sensitive cells using nanosized EphA2-targeted PEGylated liposomes." (PMID 31581483, 2019). "Overexpression of EphA2 or RacN17 in melanoma cells induces MAT like phenotype which leads to increase in tumor invasion." (PMID 28137308, 2017). "EphA2 is a member of the ephrin-receptor family of PTKs and expresses in melanoma cells with a metastatic phenotype, which is crucial to angiogenesis 59,60." (PMID 25598425, 2015). "Overexpression of EphA2 is one of the prognostic factors in progressive tumours, including lung, breast, brain, ovarian, melanoma, prostate and urinary bladder cancers." (PMID 26158630, 2015). "The MMP-laminin 5γ2 chain and other signaling regulators associated with VM (TGFβ, VE-cadherin, EphA2, PI3K etc.)are coordinately over-expressed in a number of malignancies including GBM and aggressive melanoma." (PMID 26085929, 2015). "In the present study, we demonstrated that BRAF-V600E evoked RSK-mediated EphA2 phosphorylation in melanoma cells." (PMID 26158630, 2015). "Next, we analyzed EphA2 expression in a panel of pancreatic cancer cells, melanoma cells, endothelial cells, and a hepatic cell line." (PMID 24760010, 2014). "We examined expression of SRC kinase and the 3 potential predictive biomarkers, ANXA1, CAV-1 and EphA2, in a cohort of 125 melanoma specimens." (PMID 25594008, 2014). "We examined expression of the three potential predictive biomarkers (ANXA1, CAV-1 and EphA2) in melanoma specimens by IHC." (PMID 25594008, 2014). "EphA2, an embryonic phenotype, has been confirmed as a key factor promoting VM formation through cell plasticity in melanoma." (PMID 24864260, 2014). "We detected strong EphA2 expression for pancreatic cancer cells, endothelial cells, and for 4 of 6 melanoma cell cultures." (PMID 24760010, 2014). "Moderate/strong expression of all three markers (ANXA1, CAV-1 and EphA2) was found in 21/113 (19 %) of the melanoma samples, 16/77 (21 %) of primary melanoma samples and 5/36 (14 %) of metastatic samples." (PMID 25594008, 2014). "Previous studies on melanoma have indicated that erythropoietin-producing hepatocellular carcinoma-A2 (EphA2), phosphoinositide 3-kinase (PI3K) and matrix metalloproteinases (MMPs) are the key factors for VM formation." (PMID 25202424, 2014).
melanoma (continued). "Moderate/strong expression of ANXA1, CAV-1 and EphA2 with co-expression of SRC kinase was found in 17 % of melanoma samples." (PMID 25594008, 2014). "In melanoma VM, EphA2 is phosphorylated through interactions with its membrane bound ligand, Ephrin-A1." (PMID 25202424, 2014). "EphA2 was expressed in 90/121 (74 %) of melanoma samples, and was detected more frequently in in primary samples 68/82 (83 %) compared to metastatic samples 22/39 (56 %) (p = 0.003; Chi-squared test)." (PMID 25594008, 2014). "The authors showed that EphA2 re-expression in B16 murine melanoma cells converts their migration style from a mesenchymal to an amoeboid-like nonproteolytic invasive program, giving rise to successful lung and peritoneal lymph node metastases." (PMID 23899007, 2013). "EphA2 was found to be expressed at high levels in metastatic melanoma cells in comparison with normal melanocytes." (PMID 18231102, 2008). "EPHA2 is involved in several signalling pathways and is reported to be overexpressed in many cancers, including melanoma." (PMID 16189525, 2005). "However, SHM16 stimulates the internalization of EphA2 and inhibits malignant features of melanoma A375 cells." (PMID 40236294, 2025). "Our studies showed that an Integrin/VE‐cadherin/EphA2/PI3K/MMP‐2 axis could potentially regulate VM formation in melanoma." (PMID 39036079, 2024). "If short hairpin RNAs are employed to induce specifically depletion of EphA2 in melanoma cells, where the receptor is upregulated, a large reduction of cellular viability, colony formation and migration in vitro is encountered along with a significant loss of tumorigenic capacity in vivo." (PMID 36142306, 2022). "Non-canonical EphA2 pathway has also been linked to several features of melanoma evolution (i.e., migration and invasion, metastasis, and drug resistance)." (PMID 36142306, 2022). "EPHA2 expression in melanoma was already documented in melanoma cells lines." (PMID 35626181, 2022). "In addition, VE-cadherin and EphA2 were the first two proteins identified as having a role in mediating melanoma VM." (PMID 34476217, 2021). "Furthermore, VE-Cadherin and EphA2 act in a coordinated manner in the regulation of vascular signaling pathway of melanoma cells." (PMID 33946480, 2021). "Furthermore, it has been shown that VE-cadherin can regulate the position and level of EphA2 phosphorylation, providing the first evidence that signal transduction from the plasma membrane is necessary for melanoma VM." (PMID 34476217, 2021). "What is more, in our bioinformatic analysis, melanoma cells expressed EPHA2 at levels comparable to Ewing’s sarcoma and chondrosarcoma; in melanoma cells, EPHA2 expression has been linked to the shift from mesenchymal movement to amoeboid-like movement in migration and metastasis." (PMID 34831119, 2021). "In melanoma, EphA2 is overexpressed and mediates vemurafenib resistance." (PMID 32814829, 2020). "Additionally, VE-cadherin and EphA2 are co-localized in cell-cell adhesion junctions in aggressive melanoma." (PMID 33510642, 2020). "EphA2 is also considered a growth receptor for malignant melanoma." (PMID 31581483, 2019). "Note the presence of EPHA2 that was regulated by CDH5 for vasculogenic mimicry in melanoma cells." (PMID 31324051, 2019). "For instance, EPHA2 overexpression causes oncogenic transformation of mammary epithelial cells, was found essential for tumour growth and able to mediate resistance to BRAF kinase inhibitors in melanoma." (PMID 27058903, 2016). "Expression of ANXA1, CAV-1 and EphA2 were analysed in 124 melanoma samples by immunohistochemistry." (PMID 25594008, 2014). "Co-expression of SRC, ANXA1, CAV-1 and EphA2 was detected in 35/113 (31 %) of melanoma samples." (PMID 25594008, 2014). "EphA2 was detected in 6 of the 8 melanoma cell lines tested." (PMID 25594008, 2014).
melanoma (continued). "Interestingly, elevated protein expression of ANXA1, CAV-1 and EphA2, determined by semi-quantitative immuno-blotting, correlated with dasatinib sensitivity in the melanoma cell lines." (PMID 25594008, 2014). "Importantly, YSA peptide insertion into the Ad5T/41sSK fiber resulted in a significant increase in the transduction of EphA2-positive pancreatic cancer and melanoma xenografts, indicating peptide-mediated viral entry targeting in vivo." (PMID 24760010, 2014). "However, the frequency of EphA2 was higher in primary melanomas (83 %) compared to metastatic tumours (56 %)." (PMID 25594008, 2014). "By using a multidisciplinary approach, we identified four different treatments able to induce MAT in melanoma cells: EphA2 overexpression, Rac1 functional inhibition using its RacN17 dominant negative mutant, stimulation with Ilomastat or treatment with the RhoA activator Calpeptin." (PMID 24690323, 2014). "The most convincing evidence to date for the role of protease-independent invasiveness in the process of in vivo metastasis was given by the Chiarugi lab in a series of studies analyzing the role of EphA2 in the metastasis of melanoma and prostate carcinoma cells." (PMID 23899007, 2013). "Knockdown of EphA2 in malignant melanoma cells impaired formation of the VM network." (PMID 21264258, 2011). "Moreover, down-regulation of EphA2 expression using a specific small interference RNA (siRNA) inhibits VM formation in aggressive melanoma cells." (PMID 21264258, 2011). "Expression and activation of Src kinase, FAK and EphA2 were also examined in the melanoma cells." (PMID 18823558, 2008). "Furthermore, the expression of ephrinA1 and the upregulation of its receptor, EphA2, were found during the course of melanoma progression." (PMID 18231102, 2008). "Compared to the EphA2 expression in malignant melanoma, normal tissues have low EphA2 expression, and therefore using YSA peptide-anchored nanocarriers for drug delivery may reduce off target side effects by reducing exposure of cytotoxic drugs to normal cells." (PMID 31581483, 2019). "Interestingly, recent work suggest that EphA2-ephrin-A1 signaling may support cell migration and invasion in prostate cancer and melanoma cells in this manner." (PMID 27246245, 2016). "Finally, activation of RTK may be also driven by induction of the EPHA2 signaling; in melanoma cells resistant to vemurafenib, EPHA2 overexpression seems to contribute to cell survival and viability as well as to promotion of metastasis formation." (PMID 26322273, 2015). "In conclusion, our results suggest that IHC staining for ANXA1, CAV-1 and/or EphA2 may form the basis of a biomarker panel to select melanoma patients for a biomarker-driven clinical trial of dasatinib, to better define the potential clinical benefit of dasatinib in melanoma treatment." (PMID 25594008, 2014). "In melanoma, SPINK6 activates the EGFR/EphA2 complex and downstream ERK1/2 and AKT pathways, thereby promoting tumor metastasis." (PMID 39990675, 2025). "Direct inhibition of EphA2 was shown to reduce Akt and erk (MAP kinase) phosphorylation, induce apoptosis, and efficiently reduce melanoma development in vivo." (PMID 36830852, 2023). "For example, EphA2 mediates EGFR kinase inhibitor resistance in lung cancer and mediates vemurafenib resistance in melanoma." (PMID 32814829, 2020). "The protein expression of EphA2 was significantly lower in the whole cell lysates from A375R and Sk-MEL-28R melanoma cell lines compared to A375 and Sk-MEL-28." (PMID 31581483, 2019). "Most of the genes that are upregulated in aggressive melanoma are known to be involved in angiogenesis and vasculogenesis, such as CD144, EPHA2 and LAMC2." (PMID 28137308, 2017). "Among these melanoma cell lines, A2058, A375, UACC257 and SK-MEL-2 expressed total EphA2 protein and pS-EphA2 constitutively." (PMID 26158630, 2015).
melanoma (continued). "If SRC kinase staining is added to the panel, 19/113 (17 %) of the melanomas express detectable levels of SRC kinase and have moderate/strong expression of ANXA1, CAV-1 and EphA2." (PMID 25594008, 2014). "Pearson correlation coefficient analysis was used to examine the relationship between mRNA and protein expression of ANXA1, CAV-1, CAV-2, EphA2, IGFBP2 and PTRF in the panel of melanoma cell lines." (PMID 25594008, 2014). "Seventeen percent (19/112) of melanoma samples were positive for SRC kinase expression, combined with high expression of ANXA1, CAV-1 and EphA2." (PMID 25594008, 2014). "It was previously reported that EPHA2 re-expression in B6 murine melanoma cells activates a non-proteolytic invasive program that proceeds through the activation of cytoskeleton motility, conferring a plasticity in tumor invasiveness." (PMID 35626181, 2022). "In detail, the expression of active non-canonical EphA2-S897E in melanoma cells led to MAT driven by Cdc42 activation." (PMID 33572284, 2021). "Also, ligand-independent EPHA2 signaling triggered the adoption of a therapy-induced, BRAF inhibitor resistant-metastatic melanoma phenotype through PI3K-AKT signaling." (PMID 33572284, 2021). "Microarray analysis showed that EphA2 and VE-cadherin were overexpressed in human aggressive melanoma cells but not in poorly aggressive melanoma cells 29,31." (PMID 25598425, 2015). "Reducing BMP4 activity in melanoma cells reduced VE-cadherin and EphA2 expression and failed to promote tubular structure formation." (PMID 25598425, 2015). "Thus, EPHA2 and CXCL2 potential role in cycling hypoxia-induced melanoma progression is worth further investigation." (PMID 25122487, 2014). "EphA2 expression was found in both highly aggressive uveal and cutaneous melanoma cells, but not in poorly aggressive melanoma cells." (PMID 21264258, 2011). "Although SHM16 was established by the immunization of A375 melanoma cells into mice and developed as an agonistic mAb against EphA2, SHM16 is not available to Western blot with the denatured form of EphA2, possibly due to its recognition of a structural epitope." (PMID 40236294, 2025). "Dasatinib was also reported for its capacity to inhibit EphA2, Src family kinase particularly, FAK and Crk-associated substrate that consequently abolishes migration and invasion without any significant effect on melanoma cell viability or proliferation." (PMID 33918490, 2021). "To demonstrate that upregulation of EPHA2 and MET also occurs in tumors of patients who develop resistance to BRAFi therapy we have analyzed tumor samples obtained before treatment and after progression in three melanoma patients receiving treatment with BRAFi." (PMID 29048432, 2017). "We show that the YSA peptide, binding to the pan-cancer marker EphA2, can be inserted into three positions of the chimeric fiber, resulting in strong transduction of EphA2-positive but not EphA2-negative cells of human melanoma biopsies and of tumor xenografts after intratumoral injection." (PMID 24760010, 2014). "It remains unclear why higher frequencies of EphA2- and MAGE-6-specific CD4+ T cells were identified in female patients, although it has been previously reported that female melanoma patients have a generally better prognosis (i.e., longer survival) when compared to their male counterparts." (PMID 25325015, 2014). "However, unlike that in melanoma, our study focused on the changing of cell adhesion and cell plasticity regulated by EphA2 in terms of EMT." (PMID 24864260, 2014). "While the melanoma cell lines were negative for EphA2 expression in vitro as assessed by Western Blotting, it was conceivable that they had become EphA2+ after in vivo injection, which could more easily explain the efficacy of the mEphA2 peptide-based vaccinations." (PMID 15563374, 2004). "We found that expression of ANXA1, CAV-1, CAV- 2, EphA2, IGFBP2 and PTRF mRNA did not correlate with response to dasatinib in the panel of 8 melanoma cell lines." (PMID 25594008, 2014).
prostate carcinoma (60 papers, 2007 to 2025). A carcinoma that arises from epithelial cells of the prostate gland. "Ephrin A2 (EPHA2), a tyrosine kinase receptor that is associated with aggressive prostate cancer and adverse prognosis, was detected with 14 biotinylation sites." (PMID 38053024, 2023). "The presence of VM in prostate cancer is associated with higher expression of certain related factors, like HIF1α, EphA2, ZEB1, and Sp1." (PMID 37810976, 2023). "Recent studies in vivo and in vitro in prostate cancer showed that VM development was associated with high expression of EphA2 and PI3K." (PMID 31993365, 2019). "Eph receptor expression is frequently misregulated during tumour progression and EphA2 overexpression is associated with poor prognosis in prostate cancer patients." (PMID 24795148, 2014). "A series of studies show that EphA2 is associated with VM in ESCC, gastric cancer, and prostate cancer." (PMID 40615663, 2025). "With a similar approach, cationic solid lipid nanoparticles (cSLNs) were designed to cargo anti-EphA2 siRNAs in prostate cancer." (PMID 39596256, 2024). "KIAA1199 further reduces the expression of Sema3A, increases the expression of VE-cadherin and phosphorylated EphA2, and enhances angiogenesis and vasculogenic mimicry in prostate cancer by enhancing hyaluronic acid-mediated VEGFA signaling." (PMID 37810976, 2023). "UniPR129 inhibited EphA2 autophosphorylation in human prostate cancer (PC3) cells, and it was able to modify prototypical phenotypes controlled by ephrin-A1 stimulation, including cell-rounding and migration." (PMID 35215250, 2022). "We recently demonstrated that these agonistic agents strongly reduced BxPc3 pancreatic-cancer cell migration, and suppressed tumor metastases in an orthotopic model of EphA2-driven aggressive prostate cancer." (PMID 34204178, 2021). "While both agents seemed very active, ephrinA1-Fc caused a more sustained and extensive decrease in EphA2 levels even at day 3 after treatment, compared to prostate cancer cells treated with 135H12, where EphA2 levels returned after 2 days of treatment." (PMID 33023262, 2020). "We demonstrate that pro-oncogenic EphA2 (ephrin type-A receptor 2) expression is activated in aggressive prostate cancers, and in mouse models of prostate cancers that are treated with enzalutamide." (PMID 33023262, 2020). "While not all prostate cancers express EphA2, we showed that enzalutamide induced EphA2 expression in prostate cancer cells and in a patient-derived xenograft (PDX) animal model, which provides further impetus to target EphA2 in prostate cancer." (PMID 33023262, 2020). "UniPR126 was shown to disrupt the EphA2-ephrin A1 complex and to inhibit EphA2 phosphorylation in prostate cancer cells at a level 6-fold higher (pIC50 = 4.89)." (PMID 32811512, 2020). "In the present study, we aimed at further evaluating the therapeutic potential of targeting EphA2 by agonistic agents 135H12 and ephrinA1-Fc to suppress tumor metastasis in an orthotopic nude-mouse model of prostate cancer." (PMID 33023262, 2020). "This compound blocking EphA2 phosphorylation (IC50 = 12 μM) was 4–5 times more efficient compared with LCA (IC50 = 50 μM) in inhibiting prostate cancer cells." (PMID 32811512, 2020). "After cell binding in prostate cancer cells, 1C1 rapidly induces tyrosine phosphorylation, internalization, and degradation of EphA2." (PMID 32811512, 2020). "Further functional assays revealed that LCA inhibits EphA2 autophosphorylation and blocks ephrin A1-related prostate cancer cell cytotoxicity." (PMID 32811512, 2020). "The present study further validates EphA2 as an important target in metastatic prostate cancer treatment." (PMID 33023262, 2020). "Cholanic acid has a specific and reversible interaction with EphA2’s ligand-binding domain, blocking EphA2 phosphorylation and prostate cancer cell cytotoxicity." (PMID 32811512, 2020).